SPC25 (SPC25 component of NDC80 kinetochore complex)
Description:
Acts as a component of the essential kinetochore-associated NDC80 complex, which is required for chromosome segregation and spindle checkpoint activity. Required for kinetochore integrity and the organization of stable microtubule binding sites in the outer plate of the kinetochore. The NDC80 complex synergistically enhances the affinity of the SKA1 complex for microtubules and may allow the NDC80 complex to track depolymerizing microtubules.
Synonyms: hSpc25; SPBC25; AD024; MGC22228
Tractability: Small molecule: a structure with a bound ligand is known. PROTAC: ubiquitination databases record sites on it.
Gene: Protein-coding gene on chromosome 2 (168,834,132 to 168,913,371, reverse strand). Ensembl gene ENSG00000152253.
Subcellular location: Nucleus; Chromosome, centromere, kinetochore
Subcellular location (Human Protein Atlas): Cytosol
Pathways (Reactome):
Cell Cycle: Amplification of signal from unattached kinetochores via a MAD2 inhibitory signal; EML4 and NUDC in mitotic spindle formation; Mitotic Prometaphase; Resolution of Sister Chromatid Cohesion; Separation of Sister Chromatids
Signal Transduction: RHO GTPases Activate Formins
Gene Ontology:
Molecular function: protein binding
Biological process: attachment of spindle microtubules to kinetochore; chromosome segregation; mitotic spindle organization; mitotic spindle assembly checkpoint signaling
Cellular component: cytosol; kinetochore; Ndc80 complex; outer kinetochore; nucleus
Genetic constraint (gnomAD): Loss-of-function variants: 16 observed, 21.08 expected, observed/expected ratio (o/e) 0.76, 90% interval 0.51 to 1.15. The upper end of that interval is the gene's LOEUF score, 1.15, which puts it in group 5 of 6, group 1 being the genes least tolerant of losing a copy. Missense variants: 183 observed, 197.32 expected, observed/expected ratio (o/e) 0.93, 90% interval 0.82 to 1.05. Synonymous variants: 77 observed, 72.93 expected, observed/expected ratio (o/e) 1.06, 90% interval 0.88 to 1.28.
Homologues: Orthologues: macaque SPC25 (100% identical), chimpanzee SPC25 (99% identical), pig SPC25 (90% identical), guinea pig SPC25 (89% identical), dog SPC25 (85% identical), rat Spc25 (79% identical), mouse Spc25 (75% identical), tropical clawed frog spc25 (43% identical), zebrafish spc25 (31% identical).
Diseases named in the same sentence as SPC25 in open-access papers:
SPC25 is named in the same sentence as 41 diseases in open-access papers, as found by Europe PMC text mining. Sharing a sentence is not in itself a finding about the gene and the disease. The quoted sentences say what the papers report.
hepatocellular carcinoma (11 papers, 2019 to 2025). A malignant tumor that arises from hepatocytes. "It is worth mentioning that SPC25 overexpression has been linked to unfavorable hepatocellular carcinoma (HCC) prognosis, as it fosters tumor growth and metastasis." (PMID 38605119, 2024). "The NDC80 complex is composed of four components, comprising NDC80, NUF2, SPC24, and SPC25, and aberrant expression of these four components may cause uncontrolled cell proliferation in hepatocellular carcinoma." (PMID 38102624, 2023). "Nonetheless, statistical analyses drawing upon online databases, such as TCGA, insinuate a close association between SPC25 expression and poor prognosis in patients with hepatocellular carcinoma (HCC), non-small cell lung adenocarcinoma cells, and prostate cancer." (PMID 38605119, 2024). "Recent studies have reported the overexpression of SPC25 in various tumors, including head and neck cancer, breast cancer, prostate cancer, lung cancer, hepatocellular carcinoma (HCC), colorectal cancer, and gastric cancer." (PMID 38217547, 2024). "Univariate and multivariate analysis of the relationship of SPC25 expression with overall survival among hepatocellular carcinoma patients." (PMID 32742802, 2020). "Additionally, it has been found that reducing the expression of SPC25 can significantly inhibit the progression of head and neck cancer, prostate cancer, and liver cell carcinoma." (PMID 38217547, 2024). "SPC25 plays an important role in the development of malignant tumors, but its role in hepatocellular carcinoma (HCC) is yet to be determined." (PMID 36147467, 2022). "SPC25 is a crucial component of NDC80, and its role in hepatocellular carcinoma (HCC) has been explored recently." (PMID 33408271, 2020). "In hepatocellular carcinoma (HCC), SPC25 exhibits multifaceted oncogenic roles." (PMID 40400636, 2025). "It has also been reported that PRC1 controls the expression and function of wrrag such as FANCI, SPC25, KIF11, and KIF23 via Wnt signaling in hepatocellular carcinoma (HCC)." (PMID 40400636, 2025). "However, the clinical significance of SPC25 in hepatocellular carcinoma (HCC) has not been investigated." (PMID 32742802, 2020).
lung carcinoma (9 papers, 2018 to 2025). "The NDC80 complex comprises NDC80 (Hec1 in humans), NUF2, spindle pole body component 25 (SPC25) and SPC24, among which SPC25 was recently found upregulated in lung cancer and associated with carcinogenesis, cancer cell growth and metastasis." (PMID 30408771, 2018). "SPC24 and SPC25 are associated with genomic instability and disrupted regulation of cell cycle in lung cancer, but this gene might be responsible for progression of pituitary prolactinoma." (PMID 33709028, 2021). "In lung cancer, SPC25 levels are positively correlated with tumor size and lymph node metastasis, indicating its potential to serve as a marker for tumor progression." (PMID 40400636, 2025). "Numerous studies have investigated the expression and functional implications of SPC25 across various tumor types, including breast cancer, lung cancer, gastric cancer (GC), and CRC." (PMID 40400636, 2025). "SPC25 is thought to promote lung cancer progression by regulating cell cycle progression and inhibiting apoptosis." (PMID 40400636, 2025). "The wrong allocation of chromosomes during cell division can cause birth defects, cancer, and other diseases, among which SPC25 has been found to be upregulated and increase cancer stem cell properties in lung cancer." (PMID 38217547, 2024). "Recent studies have reported on SPC25 overexpression in various tumors, including lung cancer 7, prostate cancer 8, colorectal cancer, and gastric cancer." (PMID 36147467, 2022). "The limited data presented in the literature showed that SPC25 upregulation in lung cancer and prostate cancer promotes the stemness of cancer cells 7, 8, suggesting a similar mechanism that allows SPC25 to facilitate tumorigenesis in HCC." (PMID 36147467, 2022). "From the limited supply of literature, upregulation of SPC25 was consistently detected in lung cancer and in PrC." (PMID 30408771, 2018). "Lung cancer is another malignancy in which SPC25 plays a pivotal role." (PMID 40400636, 2025). "Moreover, SPC25 was shown enriched in CSC population in lung cancer." (PMID 30408771, 2018). "The expression of GRM8, SPC25, and FAM72A was negatively correlated with favorable outcomes and also observed in other cancer types such as lung cancer and breast cancer." (PMID 35368665, 2022). "In addition to our findings on LMO1, we identified five genes (GNG4, NCAPG, SPC25, ASPM and KIF2C) that are expressed at higher levels in lung tumors relative to NATs and are significantly correlated with poor survival of lung cancer patients, suggesting possible oncogenic functions in lung cancer." (PMID 30038707, 2018).
breast carcinoma (8 papers, 2019 to 2025). "A study showed that SPC25 promotes the proliferation of breast cancer cells, and high levels of SPC25 mRNA levels are associated with high recurrence rates and low survival rates in breast cancer patients." (PMID 40454580, 2025). "Overexpression of SPC25 has been associated with advanced tumor stages, higher histologic grades, and worse overall survival (OS) and disease-free survival in breast cancer patients." (PMID 40400636, 2025). "Furthermore, the overexpression of SPC25 has been associated with poor prognosis in patients with head and neck cancer, breast cancer, prostate cancer, and HCC." (PMID 38217547, 2024). "SPC25 is also associated with poor prognosis in breast cancer patients." (PMID 35368665, 2022). "In this study, expression of the SPC25 gene was characterized in breast cancer (BC), and its effects on BC development and progression, functions in BC cells, and potential underlying mechanisms were examined." (PMID 31400751, 2019). "For instance, in breast cancer, SPC25 expression has been shown to correlate with high histological grade and poor prognosis." (PMID 40400636, 2025). "A previous study revealed that SPC25 expression in the basal breast cancer subtype is markedly upregulated when compared with that in other subtypes and that that enhanced SPC25 expression is related to decreased overall survival." (PMID 32742802, 2020). "SPC25 is highly expressed in the basal part of breast cancer with more stem cell-like cells, and SPC25 expression is related to disease-free survival." (PMID 32226507, 2020). "In this study, we investigated SPC25 expression in breast cancer (BC) and in various other human cancer types and found that SPC25 expression was upregulated in multiple tumors." (PMID 31400751, 2019). "Studies have shown that SPC25 is overexpressed in a significant proportion of breast cancer cases." (PMID 40400636, 2025). "In a previous study, SPC25 expression was higher in basal breast cancer subtypes compared with other subtypes, suggesting that it might play a key role in basal stem cell-driven breast cancer." (PMID 31400751, 2019). "Notably, SPC25 expression was much higher in triple negative breast cancer (TNBC) compared to other BC subtypes." (PMID 31400751, 2019).
prostate carcinoma (8 papers, 2018 to 2025). A carcinoma that arises from epithelial cells of the prostate gland. "SPC25 has oncogenic effects in prostate cancer and may serve as a new diagnostic and therapeutic target." (PMID 40400636, 2025). "Moreover, in malignancies such as lung cancer, prostate cancer, and breast cancer, SPC25 expression is markedly elevated, thereby fueling tumor cell proliferation." (PMID 38605119, 2024). "Their results showed that SPC25 can regulate the stemness of prostate cancer cells." (PMID 36052378, 2022). "A recent study also revealed that SPC25 knockdown promoted the apoptosis of prostate cancer cells." (PMID 32742802, 2020). "We recently showed that SPC25 is required for prostate cancer (PrC) cell proliferation and cell cycle progression, and here we investigated whether SPC25 may be a Cancer stem cell (CSC) marker in PrC." (PMID 30408771, 2018). "Statistical analysis based on online databases such as TCGA and International Cancer Genome Consortium (ICGC) 7, 10, 12, 34 suggests that SPC25 expression is closely related to poor prognosis in patients with HCC, non-small cell lung adenocarcinoma cells, and prostate cancer." (PMID 36147467, 2022).
gastric cancer (6 papers, 2015 to 2025). A primary or metastatic malignant neoplasm involving the stomach. "The regulation of SPC25 is found in colorectal and gastric cancers." (PMID 32565735, 2020). "In Kaneko's report, mRNA of CDCA1, KNTC2, SPC24 and SPC25 was overexpressed in colorectal and gastric cancers compared with the corresponding normal mucosa, siRNA-mediated knockdown of either CDCA1 or KNTC2 significantly suppressed cell growth and induced HCC cell apoptosis." (PMID 26515591, 2015).
lung adenocarcinoma (4 papers, 2019 to 2024). A carcinoma that arises from the lung and is characterized by the presence of malignant glandular epithelial cells. "And in lung adenocarcinoma, SPC25 was identified to be an independent prognostic factor for a worse survival rate." (PMID 36052378, 2022). "SPC25 upregulation can increase cancer stem cell properties in lung adenocarcinoma and independently predict poor survival in patients with lung adenocarcinoma." (PMID 32742802, 2020). "The upregulated expression of SPC25 has been reported in colorectal, gastric cancers, breast, and lung adenocarcinoma." (PMID 32742802, 2020). "For example, upregulation of spindle pole body component 25 homolog (SPC25) gene in stiff matrices is required for proliferation of H1299 lung adenocarcinoma cells by increasing the accessibility of the chromosome alignment in metaphase." (PMID 31853379, 2019). "The knockdown of SPC25 impaired the cancer stem cell properties in lung adenocarcinoma." (PMID 32742802, 2020). "However, the role of SPC25 in lung adenocarcinoma (LAUD) is unclear." (PMID 38217547, 2024).
non-small cell lung adenocarcinoma (4 papers, 2022 to 2024). Type of epithelial lung cancer arising from glandular origin. "The upregulation of SPC25 increased the cancer stem cell properties of non-small cell lung adenocarcinoma cells and was negatively correlated with survival." (PMID 35368665, 2022). "In non-small cell lung adenocarcinoma, SPC25 knockout reduced CSC characteristics and invasiveness of A549 cells." (PMID 36052378, 2022).
Alzheimer disease (3 papers, 2017 to 2020). A progressive, neurodegenerative disease characterized by loss of function and death of nerve cells in several areas of the brain leading to loss of cognitive function such as memory and language. "This cell-based litmus gene assay identified six genes (CCL20, CEMIP, IL1B, IL8, PRG2, PTGS2) as potential biomarkers of plasma quality control and the SPC25 gene as a diagnostic biomarker of Alzheimer’s disease (AD)." (PMID 29203810, 2017). "A cell-based assay revealed that the SPC25 can be a potential biomarker for Alzheimer’s disease as the expression level of SPC25 was significantly upregulated in the serum samples of patients with mild cognitive impairment." (PMID 32742802, 2020). "Interestingly, cell cycle dysregulation was recently identified in single cell RNA-seq analysis of microglia from a mouse model of Alzheimer’s disease (AD), with some of the same genes identified in our study, including Top2a, Hells, Ccne1, Spc25, Cenpe, Anln, Rsad2, and Ifitm335." (PMID 32792571, 2020). "Next, we also confirmed the significantly higher expression of the AD litmus gene (Spc25) in mouse neuronal T4 cells treated with mouse sera from 16-month-old APP transgenic mice, an Alzheimer’s disease model (APPswe/PS1dE9)." (PMID 29203810, 2017).
colorectal cancer (3 papers, 2021 to 2025). A primary or metastatic malignant neoplasm that affects the colon or rectum. "The overexpression of SPC25 in numerous cancers, including breast, lung, gastric, and colorectal cancers, has highlighted its potential as a diagnostic and prognostic biomarker." (PMID 40400636, 2025). "In recent years, studies have highlighted the overexpression of SPC25 in various cancers, including lung, breast, gastric, and colorectal cancers (CRC)." (PMID 40400636, 2025).
liver cancer (3 papers, 2020 to 2025). An epithelial or non-epithelial malignant neoplasm that arises from the liver. "Increased SPC25 expression is associated with poor prognosis in HCC and enhances cell proliferation, making it a valuable prognostic marker and a new therapeutic target for liver cancer." (PMID 40400636, 2025). "To determine the roles of SPC25 in HCC progression, we first analyzed the SPC25 expression in liver cancer tissues from the TCGA and Gene Expression Omnibus (GEO) datasets (GSE121248)." (PMID 36147467, 2022). "In order to explore the mechanism by which CDKN3 influences the occurrence and development of liver cancer, we used bioinformatics tools to screen genes related to changes in CDKN3, and SPC25, CDK1 and CCNB2 were identified." (PMID 32000807, 2020).
ovarian carcinoma (3 papers, 2021 to 2025). A malignant neoplasm originating from the surface ovarian epithelium. "Moreover, in both OVCAR3 and OVCAR8 cells, as well as their mouse xenograft tumors, we observed significant changes in the expression of downstream target genes of the Wnt/β‐catenin pathway, including those associated with ovarian cancer stem cells (OCSCs) after SPC25 overexpression or knockdown." (PMID 39488790, 2024). "SPC25 is associated with cisplatin resistance and stemness in HNSCC, promotes stemness and predicts survival in LUAD, mediates immune escape via glutamine metabolism in LUAD, and its inhibition overcomes stemness and enhances platinum sensitivity in ovarian cancer." (PMID 41375045, 2025). "Particularly, we examined if ANPEP (from EC2), CASP14 and CLEC2B (from EC3), CADM3 and NRBP2 (from EC4), and SPC25, ESCO2, and GTSE1 (from EC5) are responsible for ovarian cancer cell proliferation by the cell viability assay." (PMID 34459128, 2021). "Additionally, our study identified a number of novel markers, such as CASP14, CLEC2B, CADM3, NRBP2, SPC25, ESCO2, and GTSE1, which are upregulated in a cluster‐specific manner and critical for ovarian cancer cell proliferation and migration." (PMID 34459128, 2021).
colon adenocarcinoma (2 papers, 2020 to 2024). "Through the HPA database, we found that the expression level of commercial SPC25 in Colon adenocarcinoma (COAD) was higher than that in normal tissues." (PMID 38605119, 2024). "The expression levels of SPC25 in cholangiocarcinoma, colon adenocarcinoma, pancreatic adenocarcinoma, rectum adenocarcinoma, LIHC, and stomach adenocarcinoma were significantly higher than those in non-neoplastic tissues." (PMID 32742802, 2020).
diabetes (2 papers, 2024 to 2025). "Pathways related to beta cells were enriched in diabetes’ vQTLs (SPC25 and GCK)." (PMID 38516378, 2024).
mild cognitive impairment (2 papers, 2017 to 2020). "In addition, the SPC25 gene expression level was significantly increased in the cell-based assay using serum samples from patients with mild cognitive impairment (MCI)." (PMID 29203810, 2017).
oral cancer (2 papers, 2022 to 2025). "Hub genes VRK1, NUP37, HMMR, SPC25, and RUVBL1 were identified to be related to oral cancer at both molecular level and clinical levels." (PMID 36052378, 2022).
glioblastoma (1 paper, 2025). The most malignant astrocytic tumor (WHO grade IV). "In particular, cancers that are less well-studied, such as ovarian, and glioblastoma, should be investigated to determine whether SPC25 holds similar prognostic and therapeutic value." (PMID 40400636, 2025).
Granuloma (1 paper, 2023). A compact, organized collection of mature mononuclear phagocytes, which may be but is not necessarily accompanied by accessory features such as necrosis. "Examination of histological sections from the livers of mice confirmed that eggs of the RNAi-GFP group were capable of generating a larger size of egg-induced granuloma, whereas very small egg-induced granuloma was observed in the RNAi-SPC25 group." (PMID 36936776, 2023).
Hepatic fibrosis (1 paper, 2023). The presence of excessive fibrous connective tissue in the liver. "According to Masson staining, the RNAi-SPC25 group had significantly less hepatic fibrosis (collagen fibers in blue) than the control group." (PMID 36936776, 2023). "Moreover, in the RNAi-SPC25 group, the region of hepatic fibrosis created by a single egg was smaller than in the RNAi-GFP group." (PMID 36936776, 2023).
lymph node metastasis (1 paper, 2025). "In NSCLC, SPC25 overexpression correlates with tumor size, lymph node metastasis, and poor prognosis." (PMID 40400636, 2025).
non-small cell lung carcinoma (1 paper, 2025). A group of at least three distinct histological types of lung cancer, including non-small cell squamous cell carcinoma, adenocarcinoma, and large cell carcinoma. "Both non-small cell lung cancer (NSCLC) and small cell lung cancer exhibit elevated SPC25 levels." (PMID 40400636, 2025).